BPIFB3 (BPI fold containing family B member 3)
Description:
May have the capacity to recognize and bind specific classes of odorants. May act as a carrier molecule, transporting odorants across the mucus layer to access receptor sites. May serve as a primary defense mechanism by recognizing and removing potentially harmful odorants or pathogenic microorganisms from the mucosa or clearing excess odorant from mucus to enable new odorant stimuli to be received (By similarity).
Synonyms: C20orf185; LPLUNC3; dJ726C3.4; RYA3
Tractability: Antibody: UniProt places it where antibodies can reach, with medium confidence; UniProt predicts a signal peptide or a membrane-spanning region; its Gene Ontology location is reachable by antibodies, with medium confidence.
Gene: Protein-coding gene on chromosome 20 (33,053,903 to 33,073,847, forward strand). Ensembl gene ENSG00000186190.
Subcellular location: Secreted; Cytoplasm
Gene Ontology:
Molecular function: protein binding; lipid binding
Biological process: innate immune response
Cellular component: cytoplasm; extracellular region
Genetic constraint (gnomAD): Loss-of-function variants: 49 observed, 53.69 expected, observed/expected ratio (o/e) 0.91, 90% interval 0.73 to 1.16. The upper end of that interval is the gene's LOEUF score, 1.16, which puts it in group 5 of 6, group 1 being the genes least tolerant of losing a copy. Missense variants: 628 observed, 611.6 expected, observed/expected ratio (o/e) 1.03, 90% interval 0.96 to 1.1. Synonymous variants: 271 observed, 279.91 expected, observed/expected ratio (o/e) 0.97, 90% interval 0.88 to 1.07.
Homologues: Orthologues: chimpanzee BPIFB3 (99% identical), macaque BPIFB3 (93% identical), pig BPIFB3 (86% identical), mouse Bpifb3 (79% identical), guinea pig BPIFB3 (78% identical), dog BPIFB3 (78% identical), rat Bpifb3 (77% identical), rabbit BPIFB3 (70% identical), Caenorhabditis elegans C06E8.5 (17% identical). Paralogues in human: BPIFB4 (38% identical), BPIFB2 (26% identical), BPIFB6 (25% identical), LBP (21% identical), BPIFC (20% identical), BPI (18% identical), PLTP (18% identical), BPIFB1 (18% identical), CETP (15% identical), BPIFA1 (12% identical), BPIFA3 (10% identical), BPIFA2 (10% identical).
Diseases named in the same sentence as BPIFB3 in open-access papers:
BPIFB3 is named in the same sentence as 5 diseases in open-access papers, as found by Europe PMC text mining. Sharing a sentence is not in itself a finding about the gene and the disease. The quoted sentences say what the papers report.
ZIKV infection (2 papers, 2020 to 2022). "In addition, BPI Fold Containing Family B Member 3 (BPIFB3) as a regulator of autophagy positively regulates ZIKV infection and promotes the formation of viral replication." (PMID 32410874, 2020).
Salmonella Infections (1 paper, 2021). Infections with bacteria of the genus SALMONELLA. "In a few cases, 7-dpi upregulation mediated by the SE challenge and/or supplement in S-II, S-III, and S-IV reached a factor of ~400 to ~500 (CA2) and even ~3100 (BPIFB3), which was comparable to the maximal expression of various genes in response to Salmonella infection in other studies." (PMID 33535430, 2021).
viral infections (1 paper, 2024). "Key genes, such as APO, PLA2, BPIFB3, and members of the TRIM family, play significant roles during viral infections." (PMID 39728450, 2024).
bacterial infection (1 paper, 2022). "The BPIFB6, BPIFB4, BPIFB2, and BPIFB3 genes are the most significant because they are involved in biological signaling pathways, which play an essential role in innate immunity against bacterial infection." (PMID 36672756, 2022). "The BPIFB6, BPIFB4, BPIFB2, and BPIFB3 genes were the most significant because they are involved in biological signaling pathways, which play an essential role in innate immunity against bacterial infection." (PMID 36672756, 2022).
infection (1 paper, 2024). The state of being infected such as from the introduction of a foreign agent such as serum, vaccine, antigenic substance or organism. "In the current experiment, a decrease in the expression levels of BPIFB3 and TRIM genes was observed in the lungs of NDV-infected chicken embryos at 24 h post-infection (hpi)." (PMID 39728450, 2024).